IL1B (interleukin 1 beta)
Diseases named in the same sentence as IL1B in open-access papers (continued):
Sharing a sentence is not in itself a finding about the gene and the disease.
nephrosis (2 papers, 2015 to 2018). Pathological processes of the KIDNEY without inflammatory or neoplastic components. "Other inflammatory cytokine and chemokine activations involved in PAN-induced nephrosis, including IL-1β and MCP-1, were abolished by treatment with YQQRG." (PMID 26014479, 2015).
neurofibroma (2 papers, 2017 to 2024). An intraneural or extraneural neoplasm arising from nerve tissues and neural sheaths. "Human plexiform neurofibroma SCs also show up-regulated IL1B gene expression (GSE14038), supporting the relevance of this observation." (PMID 28256556, 2017). "Inhba, Cxcl2, Il1b, Clcf1, Lif, and Ccl5 were up-regulated in human neurofibroma SCs, and may justify further study." (PMID 28256556, 2017). "Of note, IL1B and CASP1, the proteinase necessary for cleavage and thus activation of IL1B, were also detected in neurofibroma lysates." (PMID 28256556, 2017).
neuroma (2 papers, 2023 to 2024). A tumor that grows from a nerve or is composed of nerve cells and nerve fibers. "TNF-α and IL-1β may contribute to neuroma-associated neuropathic pain." (PMID 37048560, 2023).
oligospermia (2 papers, 2023 to 2025). Decreased number of spermatozoa in the semen. "Results showed that the levels of IL-6 and IL-1β in oligospermia samples were elevated compared to those in normal samples." (PMID 40707433, 2025). "IL-1β was also shown to be statistically significant (p≤ 0.01) for oligoasthenospermia, oligospermia and asthenospermia." (PMID 37027384, 2023).
optic neuritis (2 papers, 2022 to 2025). Optic neuritis is inflammation of the optic nerve, the nerve that carries the visual signal from the eye to the brain.The conditionmay cause sudden, reduced vision in the affected eye(s). "Additionally, 670 nm light treatment downregulates NFκB and IL-1β expression, consistent with reports indicating that NFκB inhibition reduces RGC loss in optic neuritis models." (PMID 40722990, 2025). "VPA treatment of optic neuritis, reduced optic nerve mRNA expression of TNF-α and Il-1β, inhibited upregulation of phosphorylated NF-κB p65 and downregulation of IκB suggesting a suppression of the NF-κB signaling pathway." (PMID 35646919, 2022).
oral candidiasis (2 papers, 2022 to 2023). Infection of the mucosal lining of the mouth with the fungus Candida albicans. "We examined Ep and CT expression levels of the cytokines IL-1β and G-CSF, known to expand and activate neutrophils during OPC, and the chemokines KC/CXCL1 and MIP-2/CXCL2, which recruit neutrophils in response to oral candidiasis in tongue tissue 6–8." (PMID 37886517, 2023).
osteophytes (2 papers, 2015 to 2025). "COMP had an AUROC of 0.604 (0.543,0.664) for new cases of JSN, COMP, IL-1β and leptin had an AUROC 0.586 (0.524,0.646) for new osteophytes, and TNF-α, IL-1β and adiponectin had an AUROC 0.590 (0.520,0.659) for new sclerosis." (PMID 41194279, 2025).
otitis (2 papers, 2019 to 2024). "A study of pediatric otitis patients found a large amount of inflammatory factor IL-1β in the ear effusion." (PMID 38393014, 2024). "Furthermore, TLR2 deficiency leads to a decreased proinflammatory cytokine profile, including TNF and IL-1β, in a murine model of S. pneumoniae otitis, resulting in increased bacterial outgrowth, bacteraemia and death." (PMID 31700009, 2019).
Pancreatic cysts (2 papers, 2022 to 2024). A cyst of the pancreas that possess a lining of mucous epithelium. "Pancreatic cyst fluid IL-1β and serum Ngal levels were not helpful for this purpose." (PMID 38542201, 2024).
papilloma (2 papers, 2010 to 2020). A benign epithelial neoplasm that projects above the surrounding epithelial surface and consists of villous or arborescent outgrowths of fibrovascular stroma. "It was notable that iLCs from papillomas expressed significantly more IL-1β at baseline than the abdomen and foreskin iLCs (52- and 8-fold, respectively, p < 0.05), but this dropped back down to the levels seen with the other cells after overnight culture." (PMID 32210959, 2020). "Smad3 null mice are resistant to TPA induction of epidermal proliferation and two-stage skin carcinogenesis with reduced infiltration of tumor-associated macrophages and expression of IL-1β and MCP-1 in papillomas compared to wild-type mice." (PMID 21297902, 2010).
PASH syndrome (2 papers, 2022 to 2024). "The PG lesion of PASH syndrome patients shows significantly elevated levels of inflammatory cytokines and mediators, including IL‐1β, TNF‐α, IL‐17, IL‐8, MMP‐2, and MMP‐9, compared to healthy skin." (PMID 38031879, 2024).
phlebitis (2 papers, 2017 to 2018). Inflammation of a vein. "Activated and FCoV-infected monocytes can induce phlebitis through the paracrine and autocrine action of CD18, IL-1β and TNFα." (PMID 28388950, 2017).
podoconiosis (2 papers, 2024). A disease of the lymphatic vessels of the lower extremities that is caused by chronic exposure to irritant soils. "Consistent with this possibility, we observed higher levels of TNF-α and IL-1β in unstimulated culture wells and IL-1β mRNA in the peripheral blood of podoconiosis patients (manuscript in preparation)." (PMID 38448477, 2024). "These two innate cells are the predominant sources of pro-inflammatory cytokines, and the higher levels of TNF-α and IL-1β in podoconiosis patients may have resulted from these activated phagocytic cells." (PMID 39591258, 2024). "Similarly, the IL-1β levels were significantly higher in podoconiosis patients in the unstimulated wells compared to healthy controls (p = 0.005, with a median value of 445 pg/mL vs. 237 pg/mL)." (PMID 39591258, 2024). "Similarly, there were significantly higher levels of IL-1β measured in the 24 h mineral stimulation assay in podoconiosis patients in unstimulated wells compared to healthy controls, which suggests a state of inflammation in vivo." (PMID 39591258, 2024). "Hence, this suggests that the two cytokines (TNF-α and IL-1β) may work synergistically in driving the inflammatory process in podoconiosis patients." (PMID 39591258, 2024).
Postpericardiotomy Syndrome (2 papers, 2014 to 2020). A nonspecific hypersensitivity reaction caused by TRAUMA to the PERICARDIUM, often following PERICARDIOTOMY. "This 6-month study investigated the therapeutic potential of rilonacept, a once-weekly subcutaneously injected IL-1α and IL-1β cytokine trap in patients with both idiopathic and postpericardiotomy syndrome RP and in both acutely symptomatic as well as steroid-dependent clinical presentations." (PMID 33229362, 2020). "The IL-8 and IL-1β may participate in the postpericardiotomy syndrome pathogenesis, and the IL-8 concentration measurement may select patients with the risk of the PPS development." (PMID 25333927, 2014).
prostate adenocarcinoma (2 papers, 2022 to 2025). "To this end, we focus on the instrumental contribution of IL-1β in the establishment and progression of advanced prostate adenocarcinoma." (PMID 39858071, 2025). "Among them, IL-1β, IL-6, and CXCL1 have been reported to be factors of immune suppressive SASP that attract myeloid-derived suppressor cells (MDSCs) to inhibit cytotoxic NK and T cell responses in prostate adenocarcinoma." (PMID 36330438, 2022).
prostate intraepithelial neoplasia (2 papers, 2019 to 2025). A neoplastic proliferation of the epithelial cells that line the acini and the ducts of the prostate gland. "Data showed that pterostilbene treatment inhibited the conversion of high-grade prostate intraepithelial neoplasia (PIN) lesions to cancer by acting through MTA1-mediated signaling to modulate PTEN acetylation, p-Akt/Akt, AR, CyclinD1, NFκB, TGFβ and IL-1β." (PMID 40077738, 2025).
protozoal diseases (2 papers, 2021 to 2023). "Some studies have shown a remarkable elevation in IL-1β, IL-6, IFN-γ, and TNF-α cytokines in systemic protozoal diseases in cattle." (PMID 36679958, 2023). "IFN-γ, a cytokine critical for innate and adaptive immune responses against viral and protozoal infections, activates HMC3 to release pro-inflammatory cytokines, including TNF-α, IL-1β and IL-6, all of them are important transcriptional regulator of inflammasome pathways." (PMID 34106880, 2021).
ptosis (2 papers, 2011 to 2020). The drooping of the upper eyelid. "For instance, IL-1b, IL-6 and TNF-α have well documented sickness effects (e.g. ptosis, piloerection, curled body posture) that are related to hypothalamic neurochemical activity." (PMID 21745392, 2011).
pyometra (2 papers, 2015 to 2016). "Overall, transcription levels of pro-inflammatory cytokines IL-1β, IL-6 and IL-8, and of anti-inflammatory cytokines IL-10 and TGFβ were significantly higher (p < 0.0001) in pyometra endometria than in healthy diestrous endometria." (PMID 27829462, 2016). "In accordance, pyometra is characterized by endometrial tissue damage, infiltration by inflammatory cells, accumulation of pus, and increased expression of inflammatory mediators such as interleukins IL-1β, IL-6 and IL-8." (PMID 27829462, 2016). "Accordingly, the IL1B and IL8 genes were detected as overexpressed in pyometra group, being IL1B, IL6 and TNF overexpressed particularly in pyometra of hormone-treated animals." (PMID 26222498, 2015). "β-hemolytic E. coli pyometra endometria had higher gene transcription of IL-1β and IL-8 and lower gene transcription of IL-6 than non-hemolytic pyometra endometria." (PMID 27829462, 2016). "β-hemolytic E. coli pyometra endometria had higher gene transcription of IL-1β and IL-8 and lower gene transcription of IL-6 than non-hemolytic E. coli pyometra endometria (p < 0.01)." (PMID 27829462, 2016). "However, hemolytic E. coli pyometra endometria had higher transcription levels of IL-1β and IL-8 and lower transcription levels of IL-6 than non-hemolytic E. coli endometria (p < 0.01)." (PMID 27829462, 2016).
radiation dermatitis (2 papers, 2019 to 2020). "The reduced IL-1β production that we observed in TRPM2−/− mice may therefore be sufficient to protect them from radiodermatitis." (PMID 30483886, 2019).
rectal cancer (2 papers, 2023 to 2024). A primary or metastatic malignant neoplasm that affects the rectum. "A Russian case–control study revealed a significant association between IL1B SNP rs1143623 (− 1473G>C) and risk of rectal cancer [co-dominant model: OR (95% CI) = 1.67 (1.06–2.63), P = 0.048]8." (PMID 37147350, 2023).
respiratory syncytial virus infection (2 papers, 2019 to 2021). "However, a previous study on respiratory syncytial virus infection in animal models suggests that ERS in lung tissue increases IRE‐1expression, resulting in caspase‐1 cleavage and mature IL‐1β production." (PMID 30378252, 2019).
Respiratory tract infection (2 papers, 2013 to 2016). An infection of the upper or lower respiratory tract. "Our findings concerning caspase-1 dependent IL-1β release suggest a role for the inflammasome in respiratory tract infections with NTHi which may be relevant for the pathogenesis of bacterial exacerbations in COPD." (PMID 23840534, 2013). "Of noteworthy interest is the up-regulation of IL-1β and NLRP3 in samples from children with the most severe respiratory tract infection." (PMID 27171557, 2016).
retinal dystrophies (2 papers, 2017 to 2020). "Although subretinal MPs are implicated in photoreceptor toxicity via IL-1β secretion, one cannot rule out the involvement of other retinal cell types in modulating inflammation during retinal dystrophies." (PMID 33246504, 2020). "Targeting IL-1β may prove efficacious in broadly suppressing chemokine-mediated inflammation in retinal dystrophies such as AMD." (PMID 28438165, 2017).
rheumatic heart disease (2 papers, 2018 to 2022). An autoinflammatory condition following an infection with Group A Beta Hemolytic Streptococcus (GABHS), in which the heart is attacked by antibodies formed in reaction to a recent GABHS infection. "The comparison between congenital heart disease and rheumatic heart disease in terms of the IL-1β and IL1R1 expression levels revealed a difference between these two types of valvular heart diseases." (PMID 29548280, 2018).
salivary gland tumors (2 papers, 2022 to 2025). "Our results also showed that not only IL1-β expression in salivary gland tumors was elevated, but also both CD44s and CD44v6 were increased." (PMID 35626430, 2022). "Our findings also indicated that IL-1β was robustly increased in malignant salivary gland tumors." (PMID 35626430, 2022). "Only IL-1β may play a crucial role in the aggressiveness of salivary gland tumors, because it was expressed only in the malignant group and its expression was high in the high-grade malignancy." (PMID 35626430, 2022). "Overall, these findings indicate that IL-1β may play a significant role in the aggressiveness of salivary gland tumors, as it was expressed only in the malignant group as well as its expression was high in the samples of the high-grade malignant group of salivary gland tumors." (PMID 35626430, 2022). "Therefore, IL-1β could be a biomarker for investigating the aggressiveness in salivary gland tumors." (PMID 35626430, 2022). "However, IL-1β alone may play a crucial role in the aggressiveness of salivary gland tumors as this cytokine was expressed only in the malignant group with high expression associated with high-grade malignancy." (PMID 35626430, 2022). "Collectively, IL-1β could be a factor linking malignancy and inflammation of salivary gland tumors." (PMID 35626430, 2022). "Therefore, our findings suggest that CD44s, CD44v6, and CXCR2 might be involved in the release of IL-1β in salivary gland tumors, and IL-1β may play a crucial role in the promotion of the aggressiveness of salivary gland tumors." (PMID 35626430, 2022). "In salivary gland tumors, there has been an increase in the expression of CD44s, CD44v6, CXCR2, and IL-1β." (PMID 35626430, 2022). "In patients with salivary gland tumors (WT and PA), various chemokines have been determined, including CCL28, CXCL10, CXCL12, CCL18, and CXCL1, as well as pro-inflammatory cytokines such as IL-1β, IL-6, IL-4, IL-17, and IL-33." (PMID 40807046, 2025). "The levels of IL-1β, CXCL1, and CXCR2 in salivary gland tumors were investigated in this study." (PMID 35626430, 2022).
schwannoma (2 papers, 2019 to 2021). A benign, usually encapsulated slow growing tumor composed of Schwann cells. "Previous studies revealed that lipopolysaccharides (LPS) treatment of the schwannoma in vitro improved the level of NFκB, IL-1β, pSTAT3, and IL-6 cytokines to activate an immune reaction." (PMID 31026579, 2019).
scoliosis (2 papers, 2017 to 2025). A congenital or acquired spinal deformity characterized by lateral curvature of the spine. "Notably, knockdown of NOD-like receptor family pyrin domain containing 3 (NLRP3) has been shown to protect against PMD and scoliosis by remarkably inhibiting pyroptosis, apoptosis, and IL-1β expression in paravertebral muscle cells." (PMID 40722201, 2025).
selenium deficiency (2 papers, 2021 to 2025). A nutritional deficiency disease resulting from inadequate selenium levels in the body, which can lead to impaired function of selenoproteins essential for antioxidant defense and thyroid hormone metabolism. "Selenium deficiency increases oxidative stress and increases inflammatory marker expression (iNOS, IL-1β, IL-12, IL10, PTGE, and NF-κB) and reduces the synthesis of antioxidant enzymes (CAT, T-AOC, SOD, and GSH-Px) in macrophages in vitro." (PMID 40681871, 2025). "In commercial broilers, selenium deficiency reduced the content of soluble IgA in the duodenal mucosa and increased the level of pro-inflammatory cytokine IL-1β." (PMID 34484164, 2021).
septic peritonitis (2 papers, 2017 to 2019). Septic peritonitis is an inflammatory condition of the peritoneum that occurs secondary to microbial contamination. "Septic peritonitis induced significant impairment of learning memory and exploratory activity, which was associated with a higher expression of IL-17A, IL-1β, and TNF-α in the brain homogenate." (PMID 31686986, 2019). "In the present study, we found that septic peritonitis induced a significant increase in IL-17A, IL-1β, and TNF-α in brain homogenate, and the enhanced inflammation was strongly associated with the deterioration in cognitive functions and exploratory activity." (PMID 31686986, 2019). "To get insight into the influence of gzmA and gzmB deficiency on the local inflammatory response elicited during septic peritonitis, we measured proinflammatory (TNF-α, IFN-γ, and IL-1β, IL-6) and anti-inflammatory (IL-10) cytokines as well as MCP-1 and KC levels in PLF." (PMID 28694562, 2017).
sexually transmitted infections (2 papers, 2022 to 2024). "High sialidases and prolidases levels are also associated with elevated vaginal IL-1β, leading to tissue damage and increased susceptibility to sexually transmitted infections (STIs)." (PMID 38495652, 2024).
Sézary syndrome (2 papers, 2023 to 2024). "Increased serum levels of IL-18 were also detected in Sézary syndrome patients, while the LNs of patients with advanced-stage disease showed an upregulation of IL-18 and downregulation of IL-1β." (PMID 38397043, 2024). "Overall, the present findings showed compartmentalized expressions of IL-1B and IL-18 and provided the first evidence of their imbalance in patients with Sézary syndrome." (PMID 36902104, 2023). "However, in the dermal layer, IL-18 showed increased expression in Sézary syndrome patients, while IL-1β levels were comparable among patients and controls." (PMID 38397043, 2024). "Whether the downregulation of IL-1B could be a tumoral escape to avoid pyroptosis provides a potential avenue to better understand the immunopathogenesis of Sézary syndrome." (PMID 36902104, 2023). "Herein, to verify whether the expression of inflammasome components could be altered by Sézary syndrome, we assessed the expression of NLRP1, NLRP3, AIM2, IL-1B and IL-18 by immunohistochemistry in the epidermal and dermal layers of skin from SS patients." (PMID 36902104, 2023).
sialadenitis (2 papers, 2021 to 2024). Sialadenitis is an infection of the salivary glands. "Moreover, IL-1α and IL-1β have been detected in the acinar and ductal cells of the minor salivary glands of patients with SS and sialoadenitis." (PMID 38999930, 2024). "These cells produce IL-1β, IFNγ, and TGFβ, which activates fibroblasts and alternatively activated (M2) macrophages, thereby inducing fibrosis in IgG4-related dacryoadenitis and sialadenitis." (PMID 34391459, 2021).
simian immunodeficiency virus infection (2 papers, 2023 to 2024). An infection affecting monkeys, chimpanzees, and other non human primates caused by a HIV-like virus. "Abundant IL-1β is expressed in Paneth cells under intestinal homeostasis, and Paneth cell-derived IL-1β causes severe damage to intestinal epithelial barrier in simian immunodeficiency virus infection." (PMID 37582766, 2023).
Sleep apnea (2 papers, 2013 to 2025). An intermittent cessation of airflow at the mouth and nose during sleep is known as sleep apnea. "Based on prior evidence for their involvement in the regulation of sleep function and in pro-inflammatory physiology of sleep-disordered breathing, we selected TNF-α, IL-1β, and IL-6, to include as the basic explanatory inflammatory markers in our model." (PMID 23382975, 2013).
small intestinal disease (2 papers, 2021 to 2022). "In our experiment, NSAID-induced small intestinal disease model rats intervened by berberine showed significantly change in HTR4, F2RL3, NPY, CRHR2, IL1b, VIP, AQP8, NOS1." (PMID 34284820, 2021). "For the first time in our study the connection between SIBO and elevated intestinal IL-1β levels was examined, regardless of the presence of other small intestine disorders." (PMID 35630404, 2022).